LINC01732 (long independently transcribed non-coding RNA 1732)
Gene: Long non-coding RNA gene on chromosome 1 (181,104,688 to 181,197,932, forward strand). Ensembl gene ENSG00000237292.
Diseases named in the same sentence as LINC01732 in open-access papers:
LINC01732 is named in the same sentence as 1 disease in open-access papers, as found by Europe PMC text mining. Sharing a sentence is not in itself a finding about the gene and the disease. The quoted sentences say what the papers report.
tumor (1 paper, 2022). "In particular, most of the mRMR genes (n = 7) were obtained from the differential gene expression analysis (DEA) comparing normal tissues versus primary tumor samples, with a larger number of upregulated genes, including the mRMR genes HHLA2, LINC01732, SAA1, AL353637.1, and ZIC2." (PMID 35565241, 2022).